ITGA5 (integrin subunit alpha 5)
Diseases named in the same sentence as ITGA5 in open-access papers (continued):
Sharing a sentence is not in itself a finding about the gene and the disease.
endothelial dysfunction (1 paper, 2024). In vascular diseases, endothelial dysfunction is a systemic pathological state of the endothelium (the inner lining of blood vessels) and can be broadly defined as an imbalance between vasodilating and vasoconstricting substances produced by (or acting on) the endothelium. "Thus, elevated macrophages–ECs and cholangioctes–ECs interactions via Nampt-Insr and Nampt-Itga5/Itgb1 were found in CHB mice livers, indicating the role of VISFATIN/Nampt- NF-κB axis in endothelial dysfunction and the Insr/Itga5-VEGF axis in angiogenesis." (PMID 39000126, 2024).
Insulin resistance (1 paper, 2023). Increased resistance towards insulin, that is, diminished effectiveness of insulin in reducing blood glucose levels. "In addition, several energy metabolic processes, such as the PI3K-Akt pathway (EPHA2, FLT4, ITGA5, and LPAR6), cholesterol metabolism (APOE and CD36), and insulin resistance (FOLR1, CALM14, and PPP1R3A), were enriched in ApoE4 mice." (PMID 36720919, 2023).
ischemia (1 paper, 2019). A hypoperfusion of the BLOOD through an organ or tissue caused by a PATHOLOGIC CONSTRICTION or obstruction of its BLOOD VESSELS, or an absence of BLOOD CIRCULATION. "In the present study, mRNA levels of Itga5—encoding the α-subunit of α5β1 integrin—failed to provide a significant reaction with reference to the non-affected hemisphere but were found to increase from 4 to 24 h of ischemia." (PMID 31089963, 2019).
ischemic cardiomyopathy (1 paper, 2023). Ischemic cardiomyopathy is a cardiomyopathy in which a weakness in the muscle of the heart due to inadequate oxygen delivery to the myocardium with coronary artery disease being the most common cause. "Macrophage-specific ITGA5 activation through the administration of activating peptides may be a promising strategy to enhance angiogenesis in myocardial infarction and in ischemic cardiomyopathy." (PMID 37985764, 2023).
mastitis (1 paper, 2021). Inflammation of breast tissue during lactation or postpartum due to an obstructed duct or infection. "Thus, the finding that ITGA5 was down-regulated implied a possible relationship of ITGA5 in mastitis inhibition by SI treatment in dairy cows." (PMID 32865767, 2021).
metastatic melanoma (1 paper, 2024). A melanoma that has spread from its primary site to another anatomic site. "In conclusion, it is suggested that targeting integrins and TGF-β signalling, specifically ITGA5, ITGB3, PAI1, and p21, may offer promising approaches to overcoming vemurafenib resistance, thereby improving outcomes for metastatic melanoma patients." (PMID 39063187, 2024).
metastatic prostate carcinoma (1 paper, 2021). A carcinoma that arises from the prostate gland and has spread to other anatomic sites. "Among the eight integrin subunits analyzed, ITGA5, ITGAV, ITGB1, ITGB3, ITGB4, and ITGB5 were upregulated in the bone compared with the other organs, suggesting that some integrins may confer osteotropic properties on metastatic prostate cancer." (PMID 33514011, 2021).
mucinous carcinomas (1 paper, 2013). "In terms of age, ITGA5 was under-expressed according to RT-PCR, but over-expressed by TMA in patients over 60 years, while ITGA5 gene and protein levels were increased in mucinous carcinomas." (PMID 23705994, 2013).
multiple sclerosis (1 paper, 2018). A progressive autoimmune disorder affecting the central nervous system resulting in demyelination. "It was recently found that endothelial Itga5 protein levels are increased in the inflammatory EAE model of multiple sclerosis and coincide with fibrinogen leakage into the spinal cord; thus, our findings that Itga5 mRNA is upregulated with LPS treatment is not surprising." (PMID 29759062, 2018).
myocardial infarction (1 paper, 2023). Gross necrosis of the myocardium, as a result of interruption of the blood supply to the area, as in coronary thrombosis. "Next, we examined whether myeloid cell-specific ITGA5 loss affects the reparative and fibrotic response after myocardial infarction." (PMID 37985764, 2023). "ITGA5+ macrophages were first noted in the infarcted myocardium 3 days after myocardial infarction, and their number markedly increased at the 7-day timepoint." (PMID 37985764, 2023). "Although at the 7-day timepoint, scar size was comparable between Myα5KO mice and corresponding ITGA5 fl/fl controls, Myα5KO exhibited significantly larger scars 28 days after myocardial infarction." (PMID 37985764, 2023). "After myocardial infarction, iMaα5KO mice exhibited accentuated dilative remodeling, in comparison to ITGA5 fl/fl mice, evidenced by increased LVEDV and LVESV 28 days after coronary occlusion." (PMID 37985764, 2023). "Flow cytometry demonstrated that myeloid cell-specific ITGA5 loss did not affect infiltration of the infarct with myeloid cells, neutrophils, macrophages and T cells 7 days after myocardial infarction." (PMID 37985764, 2023).
osteoarthritis (1 paper, 2008). A noninflammatory degenerative joint disease occurring chiefly in older persons, characterized by degeneration of the articular cartilage, hypertrophy of bone at the margins and changes in the synovial membrane. "We identified that PPARA, BMP7, IL1B, LEP, ITGA5 and SREBP1 protein levels in osteoarthritic chondrocytes were highly correlated with BMI, suggesting the potential role of metabolic-related proteins in the development of osteoarthritis." (PMID 19011694, 2008).
ovarian adenocarcinoma (1 paper, 2019). An adenocarcinoma that arises from the ovary. "Subsequently, ITGA5-deficient cells (sgRNA2 group) were observed to form smaller aggregates and displayed a markedly decreased capacity for adhesion compared with control HGSOC cell line OV90 and the ascites-derived ovarian adenocarcinoma cell line SKOV3." (PMID 30710055, 2019).
Parkinson disease (1 paper, 2024). A progressive degenerative disorder of the central nervous system characterized by loss of dopamine producing neurons in the substantia nigra and the presence of Lewy bodies in the substantia nigra and locus coeruleus. "The expression of integrin 5 (Itga5) is dramatically decreased in mice with MPTP-induced Parkinsonism, according to our findings." (PMID 38993558, 2024).
pulmonary neuroendocrine neoplasms (1 paper, 2023). "In a recent study, the up-regulation of six fibrogenic genes (COL5A2, COL1A2, COL3A1, ITGA5, ITGB1, and ITGB1) in pulmonary neuroendocrine carcinoma and the down-regulation of pulmonary neuroendocrine neoplasms were strongly related to no metastasis and overall survival." (PMID 37047300, 2023).
renal cell carcinoma (1 paper, 2020). "Studies have previously reported NRP1 to complex with ITGA5 in HUVECs and NRP2 to complex with ITGA5 from co-cultures between HUVECs and renal cell carcinoma." (PMID 32528960, 2020).
skin cutaneous melanoma (1 paper, 2022). "Thus, among the selected candidate genes we identify the ITGA5 gene as the one most likely involved in the skin cutaneous melanoma." (PMID 36175857, 2022).
Ta (1 paper, 2012). "This suggests a role other than migration/invasion for ITGA5 since Ta tumors do not have a high invasive potential." (PMID 22724020, 2012).
tongue squamous cell carcinoma (1 paper, 2023). A squamous cell carcinoma that arises from the tongue. "ITGA5 expression is upregulated in tongue squamous cell carcinoma (TSCC) and the knockdown of ITGA5 suppresses the proliferative, migrative and invasive capabilities of TSCC cells." (PMID 36742137, 2023).
uveal melanoma (1 paper, 2023). A melanoma derived from melanocytes of the uveal tract. "Considering the identification of ITGA5 as a high-risk gene exhibiting a maximum absolute hazard ratio (HR) in uveal melanoma (UVM) patients, we conducted additional in vitro experiments to elucidate the specific role of ITGA5 in UVM." (PMID 37822877, 2023).
Werner syndrome (1 paper, 2012). "Senescent fibroblasts isolated from patients with Werner syndrome, a premature aging disorder, express reduced levels of ITGA5." (PMID 22289652, 2012).
ZIKV infection (1 paper, 2023). "The presence of SOX2 was further associated with an enhanced oncolytic effect promoting viral entry and ZIKV infection, in association with ITGA5." (PMID 37686355, 2023). "In particular, it was demonstrated that SOX2 promotes ITGA5 and enhances ZIKV infection." (PMID 37686355, 2023).
tumor (198 papers, 2010 to 2026). "Our findings suggest that the increased HIF-1α, LOX and ITGA5 expression in the tumor microenvironment is associated with decreased PFS, potentially reflecting resistance to treatment." (PMID 39857068, 2025). "This applies to but not restricted to the correlation of the inflammation score and various tumor features, and the association of ITGA5/SERPINE1 and the estimated infiltration levels of TAM/TIM sub-clusters." (PMID 40458391, 2025). "ITGA5 is particularly strongly associated with angiogenesis and its impact on the tumor microenvironment." (PMID 41148856, 2025). "ITGA5 has been previously reported as a marker of tumor‐specific keratinocytes (TSK) in SCC and associated with recurrence and migration." (PMID 40776410, 2025). "Further growing research has substantiated the enhanced expression of ITGA5 in various malignancies, establishing its association with tumour advancement." (PMID 39865173, 2025). "What is more, expression of ITGA5 was associated with an increased infiltration to the tumor core of CD4 + T cells, macrophages, neutrophils and dendritic cells." (PMID 37284199, 2023). "In turn, CAFs activated by ITGA5-overexpressing tumor cells secrete TGFβ-associated factors EGF, IP-10, IGFBP-3, BDNF, Flt-3 LG, FGF-7, IL-12, MIF and leptin." (PMID 35682890, 2022). "To assess the effects of loss of ITGA5 on tumor growth in vivo, we used CRISPR/Cas9 technology to knock down ITGA5 in SKOV3 cells." (PMID 30710055, 2019). "The more aggressive PRCC2 was associated with modest upregulation of ITGA5, a fibronectin receptor known to promote tumor progression in ccRCC." (PMID 27705936, 2016). "In the present study, our gain-of-function and loss-of-function experiments showed that ITGA5 is a master regulator of anoikis in tumor cells." (PMID 25537511, 2015). "Additionally, they found link between ITGA5 and immune cells, particularly activated mast cells, tumor-associated macrophages (TAMs), and Th2 and M2 cells." (PMID 41148856, 2025). "Moreover, a Sankey diagram based on IHC score showed that larger tumor size was associated with high ITGA5 and dead status of patients." (PMID 36999964, 2023). "Linear regression analysis indicated that while ITGA5 had positive correlation with Breslow thickness (as a continuous variant) ITGA2 was in strong significant inverse correlation with the Breslow thickness of the tumor." (PMID 36091936, 2022). "In addition, ITGA5 expression level was significantly associated with tumor purity and immune infiltration levels of different immune cells in gastrointestinal tumors." (PMID 33711961, 2021). "In an experiment on HNSC cell lines, after inhibiting the expression of ITGA5, the proliferation ability of tumor cells significantly decreased, accompanied by a reduction in the activity of the PI3K signaling pathway." (PMID 41602372, 2026). "This study presents a novel cyclic peptide inhibiting ITGA5-mediated tumor–stroma interaction and thereby reduce desmoplasia and resistance, ultimately enhancing chemotherapy efficacy in PDAC." (PMID 41584360, 2026). "In the present study, we designed a cyclic peptide to effectively block ITGA5 and thereby inhibit tumor-stroma crosstalk in PDAC and improve chemotherapy efficacy." (PMID 41584360, 2026). "The results showed a significant reduction in tumor growth in the ITGA5/ITGB1 double-knockdown group, indicating that these integrins contribute to OC progression." (PMID 40770810, 2025). "ITGA5 overexpression frequently correlates with poor prognosis in gastrointestinal tumors and facilitates tumor invasion via the FAK/AKT pathway." (PMID 39857068, 2025). "ITGA5 is abnormally expressed in various tumors and is closely related to the adhesion, migration, and invasion of tumor cells, as well as the generation of tumor blood vessels." (PMID 39795037, 2025).
tumor (continued). "High-risk genes (TNF, CXCL1, CCL20, ITGA5, CXCL3) typically promote tumor progression and immune evasion by inducing the expression of chemokines or modulating cellular responses to chemokines." (PMID 40517358, 2025). "We analyzed the correlation of FN1, ITGA4, ITGA5, ITGAV, ITGB1, ITGB3 and ITGB6 with disease status, risk of tumor recurrence according to the 2015 American Thyroid Association guidelines, and patient outcome." (PMID 40423510, 2025). "ITGA5 is secreted via exosomes and participates in signaling between OC cells and HPMCs, promoting a favorable microenvironment for tumor growth." (PMID 40770810, 2025). "ITGA5+ PanCK+ tumor cells, corresponding to the Carcinoma 3 cluster, were localized at the tumor–stroma boundary, and CXCR6+ FOXP3+ CD3D+ regulatory T cells were observed in close proximity within the adjacent stroma." (PMID 40776410, 2025). "These polarized expression topographies implicate complementary roles in tumor-stromal signaling - TSPAN4 as a focal signaling node versus ITGA5 as a ubiquitous adhesion mediator." (PMID 40443671, 2025). "By suppressing ITGA5, Triptolide reversed cancer progression and restored tumor-suppressive effects in a PPP2CA-knockout xenograft model." (PMID 40770810, 2025). "Exosome isolation and co-culture experiments with tumor cells and human peritoneal mesothelial cells (HPMCs) investigated ITGA5’s role in migration." (PMID 40770810, 2025). "This study highlights the prognostic significance of HIF-1α, LOX and ITGA5 expression in the tumor microenvironment, particularly in the context of KRAS/NRAS/BRAF mutation status." (PMID 39857068, 2025). "Thirteen distinct cellular subpopulations within the tumor microenvironment are identified, with STC2 and ITGA5 emerging as smoking-associated prognostic markers." (PMID 41203580, 2025). "The largest S/B ratios between tumor and normal tissues were observed in ITGA5–SBA, ITGA5–MAA, ITGA3–UEA, and ITGB1–SBA, each demonstrating a large overlap between normal and tumor tissues." (PMID 40287842, 2025). "The literature describes the importance of ITGA5 in angiogenesis, the formation of new vessels that facilitate tumor development, also in CC." (PMID 41148856, 2025). "During this critical phase, eliminating CAF expression of FN or ITGA5 is sufficient to completely account for their ability to boost tumor initiation." (PMID 39785683, 2025). "Spatial omics mapping unveiled niche-restricted overexpression of migrasome regulators TSPAN4/ITGA5 within specialized tumor microdomains, prompting systematic interrogation of their metabolic network engagement." (PMID 40443671, 2025). "For example, elevated spatial expressions of ITGA5 transcripts were detected primarily in tumor ECs, whereas ITGA7 transcripts were expressed mainly in TCs and Ast-like cells." (PMID 41366031, 2025). "On the other hand, our analysis identified ITGB1, ITGA5, and ITGA6 as key integrins significantly associated with poor prognosis in HNSC, underscoring their role in driving tumor aggressiveness and therapeutic resistance." (PMID 40021759, 2025). "This study elucidates the tumor-endothelial interactions mediated by STC2 and ITGA5 in smoking-associated LSCC, emphasizing their roles in tumor progression and vascular permeability." (PMID 41203580, 2025). "Interactions with tissue stem cells through the Col1a1/Cd93, Col1a1/Itga5, Fn1/Plaur and Itgb1/Vcan pathways underscore the critical role of the monocyte-macrophage system in tumour immunosurveillance and immunomodulation." (PMID 40046334, 2025). "Triptolide effectively disrupts this process by downregulating ITGA5, impairing tumor adhesion and invasion." (PMID 40770810, 2025). "Immunohistochemical images of ITGA5 showed weak staining in both normal and tumor tissue, however, ITGA5 levels were annotated as “not detected” in the HPA database and rejected from interpretation." (PMID 38786089, 2024).